AQP4 (aquaporin 4)
Diseases named in the same sentence as AQP4 in open-access papers (continued):
Sharing a sentence is not in itself a finding about the gene and the disease.
glioblastoma (continued). "On the same note, prominent AQP4 polarization in perivascular endfeet vanishes in various pathologic conditions, such as human glioblastoma, where AQP4 redistributes throughout the cell membrane together with α-syntrophin." (PMID 33297299, 2020). "Namely, the aggregation state of particular AQP4 isoforms had an important effect on their subcellular localization in cultured AQP4−/− cortical astrocytes and glioblastoma cells." (PMID 33297299, 2020). "This study showed that the bradykinin-BDKRB1/2 axis contributes to migration and invasion of malignant glioblastoma cells through regulation of aqp4 gene expression." (PMID 32182968, 2020). "This study further demonstrated that the bradykinin-BDKRB1/2 axis takes part in the rapid migration and invasion of glioblastoma cells due to induction of aqp4 gene expression." (PMID 32182968, 2020). "In the present study, we have also examined the effects of T3 on the expression of AQP4 in cultured human glioblastoma cells." (PMID 31019448, 2019). "It has been postulated that the AQP4 expression levels are relevant to the migration of astrocytes, indicating an enabling role of AQP4 in the infiltration of malignant glioblastoma cells." (PMID 28423683, 2017). "In general terms, AQP4 is clearly upregulated in brain tumors, including pilocytic astrocytoma and glioblastoma." (PMID 27367682, 2016). "It was suggested that AQP4 was involved in the control of glioblastoma cell migration and invasion through cytoskeleton rearrangement and cell adhesion regulation." (PMID 25886458, 2015). "The redistribution of AQP4 in glioblastoma cells was explained as a reaction to VEGF-induced vasogenic edema in order to facilitate the reabsorption of excessive fluid." (PMID 25886458, 2015). "An increased AQP4 expression has been demonstrated in glioblastoma multiforme (GBM), suggesting it is also involved in malignant brain tumors." (PMID 23950863, 2013). "In this study, we show that siRNA-mediated down regulation of AQP4 induced glioblastoma cell apoptosis in vitro and in vivo." (PMID 23950863, 2013). "The results of our animal experiments also support the role of AQP4 in the glioblastoma cells apoptosis." (PMID 23950863, 2013). "We also used another glioblastoma cell line U87 to confirm the function of AQP4 in glioblastoma cell apoptosis." (PMID 23950863, 2013). "Although the role of AQP in apoptosis is indicated by its participation in AVD, the role of AQP4 in glioblastoma apoptosis remains to be elucidated." (PMID 23950863, 2013). "In the present study, we demonstrate that AQP4 directly participated in glioblastoma cell apoptosis in vitro and in vivo." (PMID 23950863, 2013). "In this situation, the immunosuppression may have prevented the autoimmune system from identifying and targeting the glioblastoma’s AQP4, facilitating its growth." (PMID 41324079, 2025). "This review highlights the central role of aquaporin-4 (AQP4) in glioblastoma pathophysiology, extending beyond its canonical function in water transport to include tumor-cell migration, immune modulation, blood–brain barrier (BBB) disruption, and therapeutic resistance." (PMID 41324079, 2025). "In the context of human glioblastoma, the presence of AQP4 in astrocytes may significantly affect the aberrant functionality of the BBB." (PMID 39247976, 2024). "In glioblastomas and other types of astrocytomas, AQP4 expression is elevated and redistributed." (PMID 37895420, 2023). "In the light of a recent study in which we reported that AQP4ex is critical in triggering the progressive mislocalization and downregulation of AQP4 in glioblastoma, it will be of interest to evaluate whether p-AQP4ex is involved." (PMID 35625560, 2022). "A competing effect seemed to occur with denser cellularity due to cell proliferation (thus decreasing the diffusion coefficient) and higher permeability of stem cell membranes due to high AQP4 expression and activity, especially in Glioblastoma, thus increasing the ADC values." (PMID 35681782, 2022).
glioblastoma (continued). "Moreover, our confocal microscopic images showed that the distribution of elevated AQP4 was mainly located in the cytoplasm and plasma membranes of malignant glioblastoma cells." (PMID 32182968, 2020). "In addition, our present results proved that bradykinin can induce aqp4 gene expression in human and murine glioblastoma cells." (PMID 32182968, 2020). "In untreated human U87 MG glioblastoma cells, AQP4 mRNA was detected (lane 1)." (PMID 32182968, 2020). "When knocking-down AQP4 expression, glioblastoma cells instantaneously undergo apoptosis." (PMID 32182968, 2020). "In human glioblastomas, levels of AQP4 had increased by 6.8-fold." (PMID 32182968, 2020). "Expressions of aquaporin 4 (AQP4) mRNA and protein were upregulated in human glioblastomas." (PMID 32182968, 2020). "Our present study showed upregulation of AQP4 mRNA and protein expressions in human glioblastomas." (PMID 32182968, 2020). "In human glioblastomas, levels of AQP4 mRNA and protein are upregulated." (PMID 32182968, 2020). "Interestingly, repressing AQP4 expression concurrently abrogated migration of human glioblastoma cells." (PMID 32182968, 2020). "Furthermore, results of a reporter gene assay provided direct evidence proving involvement of NF-κB in bradykinin-induced aqp4 gene expression in human glioblastoma cells." (PMID 32182968, 2020). "Recently, AQP4 was functionally shown to regulate migration of glioblastoma cells." (PMID 32182968, 2020). "In this study, we sought to determine whether the administration of T3 has a regulatory effect on the expression of AQP4 in astrocytes during the normal development of the CNS and in cells derived from glioblastomas, the major type of brain tumor." (PMID 31019448, 2019). "We should be aware of the various unresolved questions regarding AQP4 in human glioblastoma." (PMID 28423683, 2017). "In addition, various studies have confirmed the increased expression of AQP4 in GBM, and the effects of down-regulated AQP4 in inducing glioblastoma cell apoptosis have also been reported." (PMID 28423683, 2017). "However, AQP4 and Kir4.1 are differentially redistributed in glioblastomas, suggesting that the mechanisms of clustering of AQP4 and Kir4.1 are distinct at the glial endfeet membrane domains." (PMID 28445150, 2017). "However, the facilitating role of AQP4 in the infiltration and invasion of malignant glioblastoma cells requires additional research." (PMID 28423683, 2017). "The authors also confirmed that AQP4 is involved in the control of glioblastoma cell invasion and migration and could be a potential therapeutic target to combat glioblastoma cell infiltration." (PMID 28423683, 2017). "Moreover, an increased AQP4 expression has been demonstrated in glioblastoma multiforme, suggesting it is also involved in malignant brain tumors." (PMID 27941618, 2016). "AQP4 was also proposed as an anti-apoptosis target for therapy of glioblastom, evidenced by the finding that siRNA-mediated down-regulation of AQP4 induced glioblastoma cell apoptosis." (PMID 25886458, 2015). "In addition we summarize that malignant glioblastoma cells as well as benign SE cells show a redistribution of AQP4 and -1 expression." (PMID 26115524, 2015). "Under pathological conditions like glioblastoma, AQP4 is up regulated." (PMID 26115524, 2015). "In this study, we tested the hypothesis that AQP4 directly participates in glioblastoma cell proliferation and apoptosis." (PMID 23950863, 2013). "Therefore, it has been hypothesized that AQP4-specific antibody coupled to a toxin might be employed to specifically harm AQP4-expressing glioblastoma cells." (PMID 38336645, 2024). "The same authors also found that T3 treatment significantly downregulates AQP4 in human glioblastoma cells, thus suggesting that higher TH concentration might have a better outcome in reducing AQP4 in brain cancer cells and, hence, in reducing tumor cell migration ability." (PMID 34070729, 2021).
glioblastoma (continued). "Furthermore, the association between α-syntrophin and AQP4 was detected in AQP4 transfected U87MG human glioblastoma cells, which natively do not express AQP4, and in human astrocyte cultures." (PMID 33297299, 2020). "The authors additionally conducted an analysis regarding the comparison between AQP4 expression in glioblastoma centers and corresponding infiltration zones to identify whether different AQP4 levels between the tumor core and the infiltration zones are correlated to patient survival." (PMID 28423683, 2017). "Because disrupting the BBB is an important pathophysiological change during the progression of glioblastoma and could play a critical role in the development of drug resistance in the treatment process, the roles of AQP4 in the BBB is an especially contentious issue." (PMID 28423683, 2017). "Thus, it is assumed that AQP4 in astrocytes may significantly contribute to the aberrant function of the BBB in human glioblastoma." (PMID 28423683, 2017). "Thus, our studies suggest that AQP4 is a critical regulator in glioblastoma cell apoptosis, and may serve as a therapeutic target for therapy of glioblastoma." (PMID 23950863, 2013). "Our results indicate that AQP4 may serve as an anti-apoptosis target for therapy of glioblastoma." (PMID 23950863, 2013). "In glioblastoma (GBM), AQP4-loaded extracellular vesicles (EVs) influence tumour behaviour." (PMID 40806720, 2025). "In glioblastoma (GBM) cells, the BK-B1R pathway mediated overexpression of aquaporin-4 (AQP4) and resulted in heightened migration and invasion." (PMID 38254732, 2024). "Expressions of AQP4 and BDKRB1/2 mRNAs in human glioblastoma were mined in The Cancer Genome Atlas (TCGA)." (PMID 32182968, 2020). "Moreover, AQP4 may serve as a new anti-apoptosis target for therapy of glioblastoma." (PMID 23950863, 2013). "Notably, an increased expression of AQP4 has been observed in glioblastoma multiforme (GBM)." (PMID 39200356, 2024). "In human glioblastoma, OAP formation is disturbed in spite of upregulated AQP4 protein." (PMID 36241864, 2022). "Besides, various studies have confirmed the increased AQP4 expression in GBM, and promoting role of the down regulation of AQP4 in inducing glioblastoma cell apoptosis has also been elucidated." (PMID 34113257, 2021). "Functional rearrangements of OAPs in glioblastomas remain to be further evaluated from the perspective of rearrangements of different AQP4 isoforms, because not all AQP4 molecules in the plasma membranes of glioblastoma cells are arranged in OAPs." (PMID 33297299, 2020). "Different expression levels of Olig2, Nogo-A, Nestin and AQP4 have no independent prognostic impact in IDH-wildtype glioblastoma and show no distribution differences regarding age, clinical status and MGMT-promoter methylation status." (PMID 32160197, 2020). "Astrocyte and glioblastoma cell culture studies revealed the tendency of T3 to negatively regulate the expression of AQP4 under the experimental conditions described herein, without significantly disrupting cellular migration." (PMID 31019448, 2019). "We show that down-regulation of AQP4 using a specific siRNA or an inhibitor, phorbol 12-myristate 13-acetate (PMA), induced apoptosis and impaired the proliferation of the LN229 and U87 Human glioblastoma cell lines." (PMID 23950863, 2013). "Furthermore, compared to primary tumors, recurrent glioblastoma tumors did not appear to exhibit significant differences in their AQP4 expression levels." (PMID 28423683, 2017). "Plasmid DNA of each mutation and M23 AQP4 were separately transfected into U-87MG glioblastoma or HEK-EBNA cell lines, and binding to AQP4 was assayed by a dual immunostaining protocol in which AQP4 was immunostained using a polyclonal Ab recognizing the intracellular AQP4 C terminus." (PMID 25792738, 2015).
glioblastoma (continued). "AQP4 expressions were also assessed in tumor and normal tissue data available on the GTEx dataset, which included STAD, LUSC, LUAD, LGG (Brain Lower Grade Glioma) and GBM (Glioblastoma multiforme) (p < 0.05)." (PMID 34113257, 2021). "The expression of aquaporin 4 (AQP4) and intermediate filament (IF) proteins is altered in malignant glioblastoma (GBM), yet the expression of the major IF-based cytolinker, plectin (PLEC), and its contribution to GBM migration and invasiveness, are unknown." (PMID 38263015, 2024). "Interestingly, we found that both endogenous and transfected AQP4 (with and without GFP) did not relocalize in response to any tonicity change in the U373 glioblastoma cell line." (PMID 26013827, 2015). "They further suggested that gamabufotalin could be a potent sensitizer of temozolomide, one of the most used clinical drugs for glioblastoma, by triggering a negative feedback loop involving the sodium pump α3 subunit (ATP1A3) and aquaporin 4 to activate p38 MAPK in glioblastoma cells." (PMID 36235115, 2022).
acute disseminated encephalomyelitis (51 papers, 2016 to 2026). Acute disseminated encephalomyelitis (ADEM) is a demyelinating disorder of the central nervous system. "Autoantibodies against MOG are implicated in pediatric MS and acute disseminated encephalomyelitis (ADEM) as well as in a subset of water channel aquaporin-4 (AQP4)-IgG seronegative neuromyelitis optica spectrum disorder (NMOSD)." (PMID 28646890, 2017). "COVID-19-associated ON showed a higher incidence of acute disseminated encephalomyelitis-associated ON (ADEM-ON, 25% vs. 0%) and a lower rate of aquaporin-4 antibody-associated ON (AQP4-ON, 0% vs. 31.4%)." (PMID 40728559, 2025). "Early in the disease course, differential diagnosis is often challenging, particularly when distinguishing monophasic episodes (such as acute disseminated encephalomyelitis or isolated optic neuritis) from chronic relapsing conditions like MS or AQP4-NMOSD." (PMID 40868427, 2025). "We found increased levels of AQP4 in the placenta and fetal membrane in a patient with acute disseminated encephalomyelitis onset in pregnancy as compared to that in a healthy control; this may be due to the activation of the HMGB1/TLR4/Nf-kB/IL-6 pathway." (PMID 35069584, 2021). "MOG-ab-positive children more frequently presented with acute disseminated encephalomyelitis, had deep gray matter lesions on MRI, had a better clinical and radiological recovery, and were less likely to have sustained disability than AQP4-ab-positive children." (PMID 33841310, 2021). "Anti-MOG antibody is predominantly detected in pediatric acute disseminated encephalomyelitis (ADEM), recurrent optic neuritis, and aquaporin-4 antibody-seronegative neuromyelitis optica spectrum disorder (NMOSD)." (PMID 28420330, 2017). "The presence of MOG-IgG also occurs in some patients that can be clinically diagnosed with aquaporin-4-IgG seronegative NMOSD, acute disseminated encephalomyelitis (ADEM), and cortical encephalitis." (PMID 34025652, 2021). "The clinical phenotypes of MOGAD overlap with those of NMOSD but include a wider range of presenting phenotypes including acute disseminated encephalomyelitis (ADEM), optic neuritis, myelitis, or demyelinating brain lesions; however, its clinical course and prognosis differ from those of AQP4-NMOSD." (PMID 38576611, 2024). "An acute disseminated encephalomyelitis–like presentation occurred at the time of the TM in 4 patients (9%) with MOG-Ab disease but no patients with AQP4-Ab disease." (PMID 31596489, 2019). "Using cell-based assays, serum MOG antibody has been shown to be primarily associated with pediatric acute disseminated encephalomyelitis (ADEM), optic neuritis (ON), transverse myelitis (TM), and aquaporin 4 antibody-negative neuromyelitis optica (NMO)." (PMID 26919719, 2016). "A percentage of acute disseminated encephalomyelitis (ADEM) and NMOSD AQP4-Ab-seronegative patients were seropositive to MOG-Ab34." (PMID 31695085, 2019). "Its heterogeneous clinical manifestations include acute disseminated encephalomyelitis (ADEM), optic neuritis, aquaporin-4-negative neuromyelitis optica spectrum disorders, transverse myelitis, cortical encephalitis, motor deficits, seizures, and cerebellar symptoms." (PMID 37370056, 2023). "More recently, antibodies against conformational epitopes of the myelin oligodendrocyte glycoprotein (MOG) have been reported in AQP4-Ab negative NMOSD as well as in pediatric acute disseminated encephalomyelitis (ADEM)." (PMID 29208041, 2017). "Additionally, a patient suspected of acute disseminated encephalomyelitis (PT-32) showed demyelination on brain biopsy but was negative for MOG, AQP4 and GFAP antibodies." (PMID 40342619, 2025).